TRIM22 (tripartite motif containing 22)
Diseases named in the same sentence as TRIM22 in open-access papers (continued):
Sharing a sentence is not in itself a finding about the gene and the disease.
head and neck squamous cell carcinoma (2 papers, 2021 to 2025). A squamous cell carcinoma that arises from any of the following anatomic sites: lip and oral cavity, nasal cavity, paranasal sinuses, pharynx, larynx, and salivary glands. "TRIM22 and BRAF are novel fusion partners; however, TRIM22 has been reported with other fusion partners in head/neck squamous cell carcinoma." (PMID 34863095, 2021).
hepatitis C (2 papers, 2011 to 2023). "TRIM22 expression is upregulated under influenza A virus (IAV) and hepatitis C virus infections, and this protein inhibits the replication of these viruses." (PMID 37446070, 2023). "qPCR analysis of liver biopsyspecimens demonstrated that these unannotated transcripts, as well as IRF1,TRIM22 and MET, were also upregulated in hepatitis C with mild inflammation andno fibrosis." (PMID 21359205, 2011). "The qPCRanalysis of biopsies showing mild hepatitis C without fibrosis provide evidence thatthe upregulation of IRF1, TRIM22, andMET are authentically due to HCV infection, and not due tomajor changes in liver tissue cell type." (PMID 21359205, 2011). "Nevertheless,our gene expression results are consistent with the activation of interferonsignaling pathways in both mild hepatitis C (without fibrosis) and HCV cirrhoticbiospecimens as observed by the significant upregulation of both liverIRF1 and TRIM22 mRNA transcripts." (PMID 21359205, 2011).
inflammatory bowel disease (2 papers, 2019 to 2022). A spectrum of small and large bowel inflammatory diseases of unknown etiology. "The identification of disease-causing TRIM22 variants that affect NOD2 signaling could lead to the development of a new diagnostic tool and could offer novel treatment opportunities for patients with very early onset inflammatory bowel diseases." (PMID 31803185, 2019).
influenza (2 papers, 2021 to 2022). An acute viral infection of the respiratory tract, occurring in isolated cases, in epidemics, or in pandemics; it is caused by serologically different strains of viruses (influenzaviruses) designated A, B, and C, has a 3-day incubation period, and usually lasts for 3 to 10 days. "That said, no research has yet been performed to confirm links between the bat TRIM22 and the Influenza viruses mentioned, which are considerably different from the H1N1 and H3N2 strains commonly utilized in studies regarding TRIM22-mediated Influenza restriction." (PMID 35215944, 2022). "TRIM22 has been observed to restrict herpesviruses, hepatitis virus B, encephalomyocarditis virus, HIV and influenza." (PMID 34552595, 2021).
liver cancer (2 papers, 2023 to 2025). An epithelial or non-epithelial malignant neoplasm that arises from the liver. "The AUC of TRIM22 diagnosis of liver cancer is 0.924, which can distinguish liver cirrhosis patients with normal HCC and normal AFP." (PMID 41472269, 2025). "PLK3, C9orf72, TRIM22, RNF152, FEZ1 and MEFV were dramatically downregulated in liver cancer patients, but upregulated by CTD treatment in HCC cells." (PMID 38017425, 2023).
liver cirrhosis (2 papers, 2020 to 2025). "Our serum proteomic analysis revealed that Trim22 in patients with normal AFP levels was reduced to 60% of the expression levels in patients with liver cirrhosis." (PMID 31979338, 2020). "As a result, we identified that serum Trim22 was significantly reduced in HCC patients compared to liver cirrhosis controls." (PMID 31979338, 2020). "Also, serum levels of Trim22 were significantly reduced in HCC patients with normal AFP compared to those with liver cirrhosis (p = 0.032)." (PMID 31979338, 2020). "Also, consistent with MRM findings, we identified that serum Trim22 was significantly reduced in HCC patients with normal AFP compared with liver cirrhosis controls." (PMID 31979338, 2020). "In addition to BMP1 (0.8, cancer/liver cirrhosis, p = 0.013), Trim22 was less abundant in HCC patients with normal AFP than liver cirrhosis patients, and this difference was statistically significant (0.6, cancer/liver cirrhosis, p < 0.001)." (PMID 31979338, 2020). "Most HCC and liver cirrhosis control patients in our study were infected with the hepatitis virus and this may have affected the protein expression of Trim22." (PMID 31979338, 2020). "Consistently, the expression of TRIM22 in liver tissue and serum of 152 Korea HCC patients mostly with HBV infection is significantly lower than that of control patients with liver cirrhosis." (PMID 41472269, 2025). "We selected Trim22 for immunoblotting analysis using patients’ sera and confirmed lower expression in HCC patients with normal AFP than liver cirrhosis controls." (PMID 31979338, 2020).
Sepsis (2 papers, 2017 to 2024). Sepsis is defined as life-threatening organ dysfunction caused by a dysregulated host response to infection. "Since Bak is an important pro-apoptotic protein, these findings indicate that in sepsis, monocyte survival may be autoregulated via the control of Bak-associated TRIM22 expression." (PMID 28079123, 2017). "In addition, it has also been reported that TRIM22 plays a crucial role in monocyte apoptosis in sepsis models." (PMID 38225560, 2024). "Taken together, these results indicate that TRIM22 plays a critical role in monocyte apoptosis by regulating Bak oligomerization and may have a potential function in the pathogenesis of sepsis." (PMID 28079123, 2017). "The correlation between TRIM22 reduction and a decrease in BAK1 levels suggests decreased apoptosis and immunosuppression in sepsis." (PMID 38225560, 2024). "However, whether TRIM30/TRIM22 affects monocyte apoptosis during sepsis remains unknown." (PMID 28079123, 2017).
Autoimmunity (1 paper, 2025). The occurrence of an immune reaction against the organism's own cells or tissues. "Their enrichment in Fate 1 implies that HPV infection may trigger interferon-driven autoimmunity, accompanied by STAB1/TRIM22 upregulation." (PMID 41035636, 2025).
B cell lymphoma (1 paper, 2022). "TRIM22 is IFN-stimulated gene (ISG) upregulated upon IFN administration and its expression in B cell lymphoma has been reported." (PMID 34996354, 2022).
cataract (1 paper, 2021). Partial or complete opacity of the crystalline lens of one or both eyes that decreases visual acuity and eventually results in blindness. "For the detection of the effects of TRIM22 in the development of cataract, we explored the expression of TRIM22 in cataract tissues." (PMID 34558381, 2021). "In this research, our results also suggested that the levels of TRIM22 were enhanced in the lens epithelial tissue of cataract sufferers." (PMID 34558381, 2021). "The results also implied that the expression of TRIM22 activated the inflammation process during the development of cataract." (PMID 34558381, 2021).
cervical cancer (1 paper, 2024). A primary or metastatic malignant neoplasm involving the cervix. "TRIM22 has been implicated in the development of various cancers, including gastric, ovarian, and cervical cancer." (PMID 39055656, 2024).
emphysema (1 paper, 2024). "TRIM22 mRNA levels were the lowest in ATII cells in emphysema." (PMID 39578839, 2024).
esophageal tumor (1 paper, 2025). "In contrast, positive TRIM22 staining was evident in both the nuclear and cytoplasmic compartments of esophageal tumor cells (consistent with previous reports) and was classified as positive staining." (PMID 40075566, 2025).
liver fibrosis (1 paper, 2016). "TRIM5 and TRIM22 SNPs are associated to increased odds of significant liver fibrosis and SVR after pegIFNα/RBV therapy in HIV/HCV coinfected patients." (PMID 27590274, 2016). "The aim of this study was to analyze whether TRIM5 and TRIM22 polymorphisms are associated with liver fibrosis inflammation-related biomarkers and response to pegIFNα/RBV therapy in HIV/HCV coinfected patients." (PMID 27590274, 2016). "The aim of this study is to analyze whether TRIM5 and TRIM22 polymorphisms are associated with liver fibrosis inflammation-related biomarkers and response to pegylated-interferon-alpha plus ribavirin (pegIFNα/RBV) therapy in HIV/hepatitis C virus (HCV) coinfected patients." (PMID 27590274, 2016). "Patients with TRIM22 rs1063303 GG genotype had higher proportion of significant liver fibrosis than patients with rs1063303 CC/CG genotypes (p = 0.021), and they had increased odds of having significant hepatic fibrosis (aOR = 2.19; p = 0.034)." (PMID 27590274, 2016).
osteoporosis (1 paper, 2023). A condition of reduced bone mass, with decreased cortical thickness and a decrease in the number and size of the trabeculae of cancellous bone (but normal chemical composition), resulting in increased fracture incidence. "The network based on hub genes showed that 3 TFs (TRIM22, CEBPG, and CEBPZ), 4 miRNAs (hsa-miR-132-3p, hsa-miR-182-5p, hsa-miR-212-3p, and hsa-miR-324-5p), and 4 drugs were involved in osteoporosis." (PMID 38260098, 2023).
ovarian carcinoma (1 paper, 2021). A malignant neoplasm originating from the surface ovarian epithelium. "And it indicated that single gene expression of IDO1, PI3 and TRIM22 could influence the chemotherapy sensitivity of ovarian cancer patients." (PMID 34736480, 2021). "The results showed that they could better predict the sensitivity of ovarian cancer patients to chemotherapeutic drugs than which based on single gene like IDO1, PI3 and TRIM22." (PMID 34736480, 2021). "Thus, the scoring model based on the gene expressions of CXCL13, IDO1, PI3, SPP1 and TRIM22 from GSE15622 dataset and constructed by lasso algorithm could better predict the sensitivity of ovarian cancer patients to chemotherapeutic drugs than which based on single gene." (PMID 34736480, 2021).
psoriasis (1 paper, 2022). An autoimmune condition characterized by red, well-delineated plaques with silvery scales that are usually on the extensor surfaces and scalp. "Another study showed that psoriasis was associated with the overexpression of antiviral genes (such as ISG15 and TRIM22) in the skin, but not in the blood." (PMID 35609018, 2022).
respiratory infections (1 paper, 2021). "We show TRIM22 to be among many antiviral effector molecules upregulated at this portal of viral entry and propose that the importance of such constitutive levels of antiviral gene expression in the control of respiratory infections has yet to be fully appreciated." (PMID 34621686, 2021).
rheumatoid arthritis (1 paper, 2023). A chronic, systemic autoimmune disorder characterized by inflammation in the synovial membranes and articular surfaces. "Furthermore, FOXC1-mediated TRIM22 governs the excessive proliferation and inflammation of fibroblast-like synoviocytes implicated in rheumatoid arthritis via the NF-κB signaling pathway." (PMID 38041172, 2023).
uterine leiomyosarcoma (1 paper, 2023). "Specifically, genes such as PGR, TRIM22, BOK, NAALADL1, AFAP1L2, and ESR1 showed MSS values greater than 5 in uterine leiomyosarcoma samples." (PMID 38066476, 2023).
Wilms tumor (1 paper, 2012). An embryonal neoplasm characterized by the presence of epithelial, mesenchymal, and blastema components. "Downregulation of TRIM22 expression is associated with progression, relapse and increased mortality in cases of Wilms tumor." (PMID 22649727, 2012).
ZIKV infection (1 paper, 2022). "To evaluate the effect of endogenous TRIM22 expression on ZIKV infection in vitro, we generated TRIM22-knockout A549 (TRIM22−/− A549) cells by CRISPR/Cas9 system, which was identified by immunoblotting." (PMID 36042495, 2022). "Here we have shown that the TRIM22 has been strongly upregulated both transcriptionally and translationally upon Zika virus (ZIKV) infection." (PMID 36042495, 2022). "We found that the antiviral function of TRIM22 plays a crucial role in counterattacking ZIKV infection." (PMID 36042495, 2022). "Western blot and immunofluorescence assay (IFA) were conducted to confirm the inhibitory ability of TRIM22 to ZIKV infection." (PMID 36042495, 2022). "We showed that TRIM22 overexpression in A549 cells could inhibit ZIKV infection, whereas TRIM22-deficient A549 cells showed enhanced ZIKV replication, implicating TRIM22 as an anti-ZIKV ISG." (PMID 36042495, 2022). "In the present study, we have presented that ZIKV infection, as well as IFN-α treatment, could upregulate endogenous TRIM22 in A549 lung epithelial cells transcriptionally and translationally." (PMID 36042495, 2022). "The results of binding and entry assays showed that TRIM22 did not affect the early step of ZIKV infection." (PMID 36042495, 2022).
infection (33 papers, 2012 to 2026). The state of being infected such as from the introduction of a foreign agent such as serum, vaccine, antigenic substance or organism. "Our results demonstrated that infection with IAV-H1N1 led to an increase in the ubiquitination of MAVS along with promoted expression of TRIM22." (PMID 40162781, 2025). "TRIM22 expression was significantly induced following infection with IAV or VSV, suggesting that TRIM22 forms a positive feedback loop with type I IFN, where increased IFN production enhances the expression of downstream effectors." (PMID 40162781, 2025). "Two of these identified ISGs, CMPK2 and TRIM22, modestly inhibit EBOVΔVP30 infection in NHSK-1-VP30 cells." (PMID 41472248, 2025). "Further investigation revealed that IAV infection led to a marked increase in TRIM22 expression at 24 h post-infection in both A549 and BEAS-2B cells." (PMID 40162781, 2025). "We collected viruses from supernatants of infected cells expressing empty vector or TRIM22 and performed a cell infection assay." (PMID 38275298, 2024). "The results showed that the infection efficiency of an equal volume of supernatant containing daughter viruses was significantly reduced after TRIM22 overexpression." (PMID 38275298, 2024). "Some of the transcripts related to infection by virus that were decreased include TRIM22, NOD2, IFITM3, and SPHK1." (PMID 36059515, 2022). "Four strains with the highest viral copy numbers (n = 4) and three strains with the lowest viral copy numbers (n = 3) were selected to evaluate TNF-α, IL-6, IFN-β, ISG-15, IFITM1, and TRIM22 expression levels at 6 h post-infection." (PMID 36146585, 2022). "We also observed an increase in TRIM22 protein levels in 7134 infection, consistent with TRIM22’s expression as an interferon-stimulated gene (lane 3)." (PMID 33524065, 2021). "Expression of IL-28, IL-29, and TRIM22 mRNA induced by the parental strain increased from 24 h to 72 h post-infection." (PMID 34068322, 2021). "In contrast, TRIM22 was continuously expressed throughout the time course of infection in MRC5t cells and remained undetectable in A549 cells, although readily detected upon IFN stimulation." (PMID 34621686, 2021). "To assess the impact of TRIM22 on the spread of infection, we infected TRIM22 depleted or control cells with IAV analysed the production of infectious virus released from infected cells over a time-course of infection." (PMID 34621686, 2021). "We conclude that the constitutive expression of TRIM22 occurs in a cell-type dependent manner, with many laboratory-adapted cell lines requiring prolonged periods of infection or immune stimulation to produce detectible levels of TRIM22 expression." (PMID 34621686, 2021). "Our observation that TRIM22 restricts the number of productive infectious events following IAV challenge suggests that this pre-existing defence can influence the outcome of infection in individual cells." (PMID 34621686, 2021). "In fact, there is evidence that the latent membrane protein 1 (LMP1) of EBV promotes an anti-viral cellular state by upregulating ISGs such as TRIM22 to prevent super-infection." (PMID 33524065, 2021). "Correspondingly, we observed a significant increase in the number of IAV (WSN) plaques in MRC5t cells depleted of TRIM22 relative to control cells at 36 hpi under equivalent infection conditions." (PMID 34621686, 2021). "Together, these data demonstrate TRIM22 to be constitutively expressed in primary cells of lung origin independently of infection or immune stimulation." (PMID 34621686, 2021). "This was consistent with the comparable TRIM22 protein levels observed in mock infection and in cells infected with HSV-1 d106 and HSV-1 KOS, both of which express the IE ICP0 protein." (PMID 33524065, 2021). "The evidence of TRIM22 antiviral activity against RSV is founded on in vitro infection of permissive cells in which TRIM22 expression was downregulated by RNA interference." (PMID 34440633, 2021).